CSF2RA (colony stimulating factor 2 receptor subunit alpha)
Description:
Low affinity receptor for granulocyte-macrophage colony-stimulating factor. Transduces a signal that results in the proliferation, differentiation, and functional activation of hematopoietic cells.
Synonyms: GM-CSF-R-alpha; GMCSFR-alpha; GMR-alpha; CD116; CSF2R; CSF2RY; alphaGMR; CDw116; CSF2RAX; CSF2RAY; CSF2RX; GMCSFR; GMR; SMDP4
Tractability: Antibody: a drug acting on it is in phase 2 or 3 trials; UniProt places it where antibodies can reach, with high confidence; its Gene Ontology location is reachable by antibodies, with high confidence; UniProt predicts a signal peptide or a membrane-spanning region. PROTAC: ubiquitination databases record sites on it; its protein half-life has been measured. Other modalities: an approved drug acts on it.
Gene: Protein-coding gene on chromosome X (1,268,779 to 1,325,373, forward strand). Ensembl gene ENSG00000198223.
Subcellular location: Cell membrane; Secreted (Isoform 3); Secreted (Isoform 4); Secreted (Isoform 6)
Pathways (Reactome):
Disease: Defective CSF2RA causes SMDP4; Defective CSF2RB causes SMDP5
Immune System: Interleukin receptor SHC signaling; Interleukin-3, Interleukin-5 and GM-CSF signaling
Metabolism of proteins: Surfactant metabolism
Signal Transduction: RAF/MAP kinase cascade
Gene Ontology:
Molecular function: protein binding; cytokine binding; growth hormone receptor activity; peptide hormone binding; signaling receptor activity; cytokine receptor activity
Biological process: cell surface receptor signaling pathway via JAK-STAT; granulocyte-macrophage colony-stimulating factor signaling pathway; positive regulation of leukocyte proliferation; cytokine-mediated signaling pathway; growth hormone receptor signaling pathway; positive regulation of cell population proliferation; positive regulation of receptor signaling pathway via JAK-STAT
Cellular component: granulocyte macrophage colony-stimulating factor receptor complex; cytosol; external side of plasma membrane; growth hormone receptor complex; plasma membrane; extracellular region; membrane
Gene-disease validity (ClinGen):
ClinGen rates the evidence that CSF2RA causes each of these diseases.
surfactant metabolism dysfunction, pulmonary, 4 (autosomal recessive): Definitive.
Homologues: Orthologues: dog CSF2RA (55% identical), chimpanzee CSF2RA (52% identical), mouse Csf2ra (28% identical), rat Csf2ra (26% identical), tropical clawed frog il5ra (20% identical). Paralogues in human: CRLF1 (16% identical), IL6ST (15% identical), PRLR (13% identical), LEPR (13% identical), IL13RA2 (12% identical), IL3RA (12% identical), CSF3R (12% identical), IL13RA1 (12% identical), OSMR (12% identical), IL31RA (11% identical), LIFR (11% identical), IL12RB2 (11% identical), and 11 more.
Diseases named in the same sentence as CSF2RA in open-access papers:
CSF2RA is named in the same sentence as 49 diseases in open-access papers, as found by Europe PMC text mining. Sharing a sentence is not in itself a finding about the gene and the disease. The quoted sentences say what the papers report.
pulmonary alveolar proteinosis (13 papers, 2014 to 2024). A rare lung disorder characterized by the filling of the pulmonary alveoli with proteinaceous material which stains positive with periodic acid-Schiff stain. "Noninfectious pneumonia is seen in adenosine deaminase (ADA) deficiency and pulmonary alveolar proteinosis (due to CSF2RA and GATA2 deficiency)." (PMID 37102642, 2023). "We identified nine patients with clinical features of pulmonary alveolar proteinosis and CSF2RA mutations." (PMID 25425184, 2014). "Pre-clinical studies investigated gene correction in hereditary pulmonary alveolar proteinosis with CSF2RA mutations and in surfactant protein B deficiency, while stem cells have been used to correct pulmonary alveolar proteinosis in CSF2RB deficient mice models." (PMID 33316882, 2020). "Juvenile pulmonary alveolar proteinosis (PAP) due to CSF2RA mutations is a rare disorder with only a few cases described worldwide." (PMID 25425184, 2014). "For example, pulmonary alveolar proteinosis (PAP) patients have autoantibodies against the soluble GMCSF cytokine preventing the normal development of macrophages in the lung, but the genetic forms of PAP have mutations in the membrane-bound GMCSF receptor (CSF2RA)." (PMID 33763057, 2021). "Another gene deregulated in lung fibroblasts with the reduced level of FENDRR is CSF2RA that was previously involved in pulmonary alveolar proteinosis." (PMID 34315444, 2021). "Similarly, mutations in the CSF2RA and CSF2RB genes in humans result in defective alveolar macrophage development and hereditary pulmonary alveolar proteinosis, which is associated with long-term respiratory insufficiency and high susceptibility to microbial infection." (PMID 35393945, 2022). "Finally, we sought to correct the CSF2RA locus in an iPSC line derived from a patient with pulmonary alveolar proteinosis (PAP), a rare life-threatening lung disease with limited therapeutic options." (PMID 38256061, 2024).
autoimmune disease (5 papers, 2016 to 2025). A disorder resulting from loss of function or tissue destruction of an organ or multiple organs, arising from humoral or cellular immune responses of the individual to their own tissue constituents. "The data suggest that dysregulation of CD99 and CSF2RA might underlie the increased frequency of autoimmune diseases in females with TS." (PMID 32210915, 2020). "Some drugs targeting CSF2RA have been developed to treat autoimmune diseases (sargramostim, KB002), diabetic foot ulcers (foreskin fibroblast), and accelerate wound closure and healing (foreskin keratinocyte)." (PMID 37726845, 2023). "Drug targeting CSF2RA, such as sargramostim, has shown clinical activity against autoimmune diseases and diverse solid tumors." (PMID 37726845, 2023).
breast carcinoma (3 papers, 2017 to 2024). "Furthermore, study reported that CSF2RA (colony-stimulating factor 2 receptor) produced in the tumor was an essential factor affecting the progression and metastasis of breast cancer." (PMID 34404444, 2021).
hereditary pulmonary alveolar proteinosis (2 papers, 2017 to 2025). "Hereditary pulmonary alveolar proteinosis (hPAP) is a rare disorder caused by mutations in the CSF2RA or CSF2RB genes, leading to impaired surfactant clearance by alveolar macrophages and subsequent respiratory dysfunction." (PMID 40486150, 2025).
influenza (2 papers, 2022 to 2024). An acute viral infection of the respiratory tract, occurring in isolated cases, in epidemics, or in pandemics; it is caused by serologically different strains of viruses (influenzaviruses) designated A, B, and C, has a 3-day incubation period, and usually lasts for 3 to 10 days. "CSF2RA-deficient patients have previously been reported with pulmonary insufficiency during infections, including Mycoplasma pneumoniae and influenza due to defective macrophage clearing of surfactant in the alveoli, interfering with gas exchange in the lungs." (PMID 38231281, 2024). "Upon influenza infection, Csf2ra–/– mice containing CSF1-cBMM–derived alveolar macrophages showed strikingly increased morbidity (i.e., loss of body weight and temperature; O2 saturation) and mortality compared with mice containing CSF2-cFLiMo–derived alveolar macrophages." (PMID 35393945, 2022). "Next, we reconstituted Csf2ra–/– mice with CSF2-cFLiMo or CSF1-cBMM to compare their ability to ameliorate influenza-induced morbidity." (PMID 35393945, 2022).
alveolar proteinosis (1 paper, 2014). "Long-term, web-based clinical follow-up of patients with CSF2RA mutation related juvenile alveolar proteinosis in registers will be a helpful tool to further extend the body of knowledge on this rare condition, and to create ready-to-trial populations for emerging therapeutic approaches." (PMID 25425184, 2014).
amyloid (1 paper, 2019). "Because our studies showed that IL-1β induced microglial proliferation and increased Csf2ra expression in MX04+ microglia, further investigation into the role of Csf2ra in IL-1β-mediated amyloid plaque clearance is warranted." (PMID 31822279, 2019).
breast tumor (1 paper, 2022). "IL-3 and GM-CSF receptor genes (IL3RA, CSF2RA, and CSF2RB) were expressed in human normal mammary epithelial and breast tumor cells at markedly higher levels compared with TSLP receptor (CRLF2)." (PMID 35657353, 2022).
chronic lung disease (1 paper, 2014). According to the definitions of the American and British Thoracic Societies, including pulmonary functional tests, X-rays, and CT scans for items such as fibrosis, bronchiectasis, bullae, emphysema, nodular or lymphomatous abnormalities. "Information on the chronic lung disease which develops in consequence of CSF2RA mutations is important for the management and prognosis of affected patients, but unfortunately rather scarce." (PMID 25425184, 2014). "One female patient (F) with a homozygous deletion of CSF2RA exons 2–13 never displayed any symptoms of chronic lung disease." (PMID 25425184, 2014).
chronic myelomonocytic leukemia (1 paper, 2016). A myelodysplastic/myeloproliferative neoplasm which is characterized by persistent monocytosis, absence of a Philadelphia chromosome and BCR/ABL fusion gene, fewer than 20 percent blasts in the bone marrow and blood, myelodysplasia, and absence of PDGFRA or PDGFRB rearrangement. "Increased levels of CSF2RA and GM-CSF signaling have been observed in hematologic malignancies such as CMML (chronic myelomonocytic leukemia) and JMML (juvenile myelomonocytic leukemia)." (PMID 27655702, 2016).
Failure to thrive (1 paper, 2017). Failure to thrive (FTT) refers to a child whose physical growth is substantially below the norm. "The majority of cases of congenital PAP due to CSF2RA abnormalities developed progressive dyspnea, exercise intolerance, tachypnea, and hypoxemia at median age of 3.5 years with failure to thrive in 55% of patients." (PMID 28464852, 2017).
fibrosis (1 paper, 2014). the formation of excess fibrous connective tissue in an organ or tissue in a reparative or reactive process. "In the adult with a CSF2RB mutation, thoracic CT scans showed the progressive appearance of traction bronchiectasis and cystic lesions suggestive of fibrosis, but no lung fibrosis was described in children bearing CSF2RA mutations." (PMID 24927752, 2014).
Insulin resistance (1 paper, 2020). Increased resistance towards insulin, that is, diminished effectiveness of insulin in reducing blood glucose levels. "CSF2RA is also located in PAR1 and its upregulation in KS is associated with insulin resistance, waist circumference, and levels of pro‐coagulatory substance PAI‐1 and cytokines (Ross, Roeltgen, Kushner, Wei, & Zinn, 2000)." (PMID 32959501, 2020).
mantle cell lymphoma (1 paper, 2016). Mantle cell lymphoma is a rare form of malignant non-Hodgkin lymphoma affecting B lymphocytes in the lymph nodes in a region called the ``mantle zone''. "LOH in a region of the PAR, which results in deletion of SHOX, CRLF2, and CSF2RA, has been observed in mantle cell lymphoma." (PMID 27655702, 2016). "Conversely, LOH of CSF2RA, along with SHOX and CRLF2, due to deletion in a portion of the PAR has been reported in mantle cell lymphoma." (PMID 27655702, 2016).
psoriasis (1 paper, 2024). An autoimmune condition characterized by red, well-delineated plaques with silvery scales that are usually on the extensor surfaces and scalp. "Furthermore, our results show that the genes mediating the development of IBD in psoriasis may be associated with the following genes CSF2RA/SOCS1/PTPN2/STAT3/IL21R, which has implications for the exploration of co-morbid targets in PsO combined with IBD." (PMID 38803495, 2024).
pyometra (1 paper, 2023). "As a granulocyte-macrophage colony-stimulating factor receptor agonist, sargramostim may be stimulating upregulated expression of CSF2RA and CSF2RB and activating mature granulocytes and mononuclear macrophages to improve anti-infection and immune function in canine pyometra." (PMID 37101686, 2023).
respiratory failure (1 paper, 2017). The significant impairment of gas exchange within the lungs resulting in hypoxia, hypercarbia, or both, to the extent that organ tissue perfusion is severely compromised. "The clinical presentation of congenital PAP due to CSF2RA defects varies from completely asymptomatic to severe symptoms with respiratory failure." (PMID 28464852, 2017).
sarcoidosis (1 paper, 2025). Sarcoidosis is a multisystemic disorder of unknown cause characterized by the formation of immune granulomas in involved organs. "A heatmap analysis further demonstrated an upregulation of key genes involved in these pathways, particularly in the progressive sarcoidosis group, including CSF2RB, CSF2RA, IL3RA, STAT5A, and STAT1." (PMID 41476976, 2025).
Sepsis (1 paper, 2022). Sepsis is defined as life-threatening organ dysfunction caused by a dysregulated host response to infection. "The main classes of drugs used for the evaluation of sepsis treatment are immunostimulatory drugs (immune targets CSF2RA/B, CSF3R), immunostimulatory cytokines (immune target is IFNGR1/2), and immunosuppressants (PDL1 and CTLA4)." (PMID 36389695, 2022). "We analyzed the immune targets of immune-related drugs to predict their potential use in sepsis and showed that nine target loci (CSF2RA/B, CSF3R, IFNGR1/2, IL7R, PDL1, CTLA4, and LAG3) differed in the high-/low-risk block." (PMID 36389695, 2022).
tumor (10 papers, 2016 to 2025). "All subsets expressed high levels of Cd11b, Csf1r, Csf2ra, Cd14, Cd64 and Cd68 confirming their initial classification as tumor-associated macrophages and monocytes." (PMID 34381732, 2021). "CSF2RA had the highest number of deep deletions consistent with their tumour promoter role in cancer development." (PMID 35488454, 2022). "Here, the crosstalk between tumor and glial cells, mediated by activation of GM-CSF/CSF2RA and AKT/PTEN pathways on both astrocytes and tumor cells, was demonstrated to play a key role." (PMID 34439289, 2021). "Moreover, the mRNA levels of csf2ra and cd43 were significantly lower in the tumor tissues of mice bearing 4T1 and LLC tumors after treatment with the combination of 5-aza-dC and TSA than those seen upon either therapy alone." (PMID 36483544, 2022). "Our results showed that at the transcriptional level, Csf2ra (GM-CSFR-α) and Csf2rb (GM-CSFR-βc) are expressed in tumor immune cells." (PMID 40075752, 2025). "CSF2RA, also known as granulocyte-macrophage colony-stimulating factor receptor alpha, and CD43, also known as sialophorin or leukocyte marker, are expressed in macrophages and are involved in tumor progression." (PMID 36483544, 2022). "Interestingly, the receptor for CSF2, CSF2RA, was not expressed on astrocytes in single culture but was significantly up-regulated when co-cultured with tumor cells." (PMID 28008153, 2017). "However, the deletion leading to the fusion of P2RY8 and CRLF2 also results in the deletion of several genes (P2RY8, CSF2RA, IL3RA, SLC25A6, and ASMTL) whose potential roles as tumor suppressors should not be discounted." (PMID 27655702, 2016).
cancer (7 papers, 2011 to 2024). A tumor composed of atypical neoplastic, often pleomorphic cells that invade other tissues. "FCGBP, FLNC, TLR7, and CSF2RA were potential antigens for developing cancer vaccination, and the patients in IS3 were considered the most suitable for vaccination in LGG." (PMID 34404444, 2021). "Further studies in larger series of patients are warranted to elucidate this question and determine the specific role of those cancer associated genes (INPP5A, CDX1, MB, CAMK2A, APOL6 vs. VPS53, FAM57A, GEMIN4, SFRS13, ELP2P, GLOD4, CSF2RA and IL3RA), differentially altered in both groups of tumors." (PMID 21811587, 2011). "Within this set of genes, a subset, notably CSF2RA, CRLF2, IL1R1, IL7R, and PDGFRB, exhibited intricate connections with the JAK-STAT pathway, which is crucial for the viability of cancer cells." (PMID 38743676, 2024). "CSF2RA and FGF12 are part of the Kyoto Encyclopedia of Genes and Genomes (KEGG) cancer pathway." (PMID 34282050, 2021).
infection (4 papers, 2020 to 2025). The state of being infected such as from the introduction of a foreign agent such as serum, vaccine, antigenic substance or organism. "For example, at 11 DoA (4 days post infection), TLR4 and CSF2RA expressions were correlated to Enterococcus and IL18 (a pro-inflammatory cytokine known for its ability to enhance the production of interferon-gamma) to Salmonella." (PMID 40079593, 2025). "Moreover, genes such as Ifr9, Ifr8, Ifr7, CSF2RA, STAT1, and STAT2 were expressed to a greater extent in the PmQ infection group than PmCQ2, and Il22, Il6, Nos2, Ccl4, Ccl5, Ifr1, Socs1, and Socs3 were increased only in PmQ infected chickens rather than PmCQ2." (PMID 32851030, 2020). "Csf2ra–/– mice lacking alveolar macrophages succumbed to infection due to lung failure." (PMID 35393945, 2022).
genetic disorder (3 papers, 2017 to 2025). "In this Taiwanese family, three genes (CSF2RA, CRLF2, and IL3RA) are homozygously deleted in the pseudoautosomal region of the human X chromosome, concordant with that PAP is a rare genetic disorder inherited at a recessive pattern." (PMID 28233860, 2017).
CSF2RA also shares sentences with these, for which no sentence is quoted: autoimmune PAP (1 paper); bacterial infections (1); colon cancer (1); complement deficiency (1); connective tissue disease (1); COVID-19 (1); Cryptococcal meningitis (1); depression (1); diabetic foot ulcers (1); glioma (1); Immunodeficiency (1); infarction (1); juvenile myelomonocytic leukemia (1); lung disease (1); lung fibrosis (1); lysinuric protein intolerance (1); metabolic disease (1); Niemann-Pick disease (1); Obesity (1); ovarian carcinoma (1); pneumococcal infection (1); primary immunodeficiency (1); rectal cancer (1); schizophrenia (1); thyroiditis (1); triple-negative breast carcinoma (1).